GPNMB (glycoprotein nmb)
Diseases named in the same sentence as GPNMB in open-access papers (continued):
Sharing a sentence is not in itself a finding about the gene and the disease.
cancer (continued). "GPNMB is a transmembrane glycoprotein that exhibits expression in various cancer types and is particularly highly expressed in the majority of cancerous tissue, indicating an unfavorable prognosis." (PMID 38706915, 2024). "GPNMB plays a key role in the anti-inflammatory and antioxidative functions as well as osteoblast differentiation, cancer progression, and tissue regeneration." (PMID 39263169, 2024). "The present findings establish GPNMB function in a non-cancer stem cell context that promotes inflammatory disease." (PMID 39052353, 2024). "Secreted GPNMB can bind to different receptors and mediate multi-faceted functions such as bone remodeling, tissue regeneration, modulation of inflammation, and cancer inhibition/metastasis." (PMID 38789534, 2024). "This approach is exemplified here using anti-GPNMB Ab that is already proven safe when it is applied to stem cell dysfunction in cancer." (PMID 39052353, 2024). "Among the factors that induce cancer stemness, glycoprotein NMB (GPNMB) is one of the most crucial proteins." (PMID 38935134, 2024). "It has also been reported that increased levels of GPNMB play an important role in bone metastasis and malignant tumors." (PMID 38790981, 2024). "Glembatumumab vedotin (CDX-011) is an antibody–drug conjugate that delivers the drug into cancer cells via glycoprotein NMB (gpNMB), resulting in cancer cell death." (PMID 37860188, 2023). "GPNMB has aroused overriding interest from researchers by virtue of its aberrant expression in cancers and the correlation with multiple biological processes composing of tissues’ regeneration and cell differentiation." (PMID 36820063, 2023). "Normally located intracellularly, gpNMB is overexpressed on the cell surface of cancer cells, making it an ideal target for ADCs." (PMID 36900378, 2023). "Recent studies have generated a more complex picture regarding the expression of GPNMB in various cancer progression, including lung cancer, ovarian cancer, stomach cancer, and breast cancer." (PMID 37112900, 2023). "GPNMB is overexpressed in a number of cancer types and was first shown to be transcriptionally regulated by MITF, but subsequently was identified as a direct transcriptional target of TFE3 and is highly expressed in TFE3-fusion RCC." (PMID 37095531, 2023). "High expression of both GPNMB and VCAM-1 has been associatedwith poor prognosis in patients, indicating a need for immunotherapiestargeting these proteins on cancer cells." (PMID 37067377, 2023). "gpNMB is a type 1 transmembrane protein that is overexpressed in numerous cancers, including 30–41% of TNBC." (PMID 36900378, 2023). "This is the first report of GPNMB or VCAM-1-specifichuman VH domain antibodies as candidates for cancer immunotherapy." (PMID 37067377, 2023). "GPNMB can promote tumorigenesis and development in various malignant tumours as a newly discovered transmembrane protein." (PMID 36090016, 2022). "The glycoprotein NMB, or GPNMB, has been shown to be overly expressed in several human cancers, including NSCLC." (PMID 36359256, 2022). "In our study we obtained evidence that the protein GPNMB also stimulates in cancer cells several other crucial pathways, such as MAPKs, AMPK and Src, in addition to STAT5." (PMID 34583655, 2021). "Our group reported that GPNMB is actively transcribed when macrophages are co-cultured with cancer cells; furthermore, it is preferentially expressed by M2 macrophages and TAMs in mouse experimental tumors are positive for GPNMB." (PMID 34583655, 2021). "GPNMB is constitutively expressed through most cell types and tissues, and its expression can be increased in cancer cells." (PMID 34054862, 2021). "Some studies have shown increased levels of GPNMB in pro-inflammatory conditions, such as LPS treatment, and in pathological conditions, such as neurodegenerative diseases and cancer." (PMID 34054862, 2021).
cancer (continued). "GPNMB is important for the invasion and metastasis of several cancers and plays diverse roles in normal cells, such as T-cell inactivation and the promotion of the specialization of osteoclasts and osteoblasts." (PMID 34639184, 2021). "Among the factors expressed by TAMs and inducing cancer cell stemness, the protein GPNMB occupies a special place." (PMID 34583655, 2021). "Transmembrane protein GPNMB has been reported overexpressed preferentially in many types of cancer tissues relative to normal tissues." (PMID 34108545, 2021). "GPNMB encodes the protein transmembrane glycoprotein NMB, which is a transmembrane protein enriched on the cell surface of various cancer cells, including melanoma cells." (PMID 32210791, 2020). "In the present study, we validated six direct targets of EZH2 that are GPNMB, PMEPA1, CoL5A1, VGLL4, POMT2 and SUMF1 associated with cancer related pathways." (PMID 30760814, 2019). "Emerging studies have generated a more complex picture regarding the expression of GPNMB in various cancer progression, including lung cancer, ovarian cancer, stomach cancer and breast cancer." (PMID 30671053, 2018). "The data we presented here clearly display that GPNMB protein level significantly correlated with advanced cancer stages." (PMID 30400781, 2018). "It is worth noting that a correlation between higher methylation of GPNMB promoter at more advanced cancer stages samples was observed." (PMID 30400781, 2018). "Research studies of GPNMB expression in specific cancer cells require careful evaluation because the outcomes seem to be context specific and dependent on tissue types." (PMID 30400781, 2018). "An expanding number of studies are evaluating the mechanism of GPNMB in cancer biology, determining its role and exploring the relationship of its expression and pro-invasive pro-metastatic phenotype in different malignancies." (PMID 30400781, 2018). "We show that HLA-DRhigh cells produce GPNMB, a soluble mediator expressed by highly aggressive tumors and now a putative target for cancer therapy." (PMID 29123519, 2017). "Meanwhile, siRNA-mediated knockdown of GPNMB/OA in cancer cells significantly reduced GPNMB/OA ECD protein shedding, migration, invasion and adhesion to extracellular matrix materials." (PMID 26883195, 2016). "CDX-011 is an anti-GPNMB/OA antibody-drug conjugate whose efficacy is proportional to the levels of cell surface GPNMB/OA expressed on cancer cells." (PMID 20711474, 2010). "In conclusion, our study confirms the hypermethylation of cancer candidate genes as biomarkers and a higher methylation profile of GPNMB, ICAM5, and CHD5 genes in AA was observed." (PMID 19750230, 2009). "GPNMB (glycoprotein nonmetastatic melanoma protein B) is a type I transmembrane glycoprotein expressed in many cell types and tissues, including macrophages, microglia, osteoclasts, melanocytes, and some cancer cells." (PMID 41406219, 2025). "Progress Compared to normal tissues, GPNMB is expressed at higher levels in cancer tissues." (PMID 41180454, 2025). "Notably, high GPNMB expression in TAMs is closely correlated with poor prognosis in various cancers." (PMID 40038549, 2025). "GPNMB, an endogenous transmembrane protein, has emerged as a critical positive contributor to human carcinogenesis and is present at high levels in various types of cancers, thereby targeting GPNMB as an attractive strategy against cancer." (PMID 38924029, 2024). "Additionally, our findings indicate that GPNMB plays an important role in promoting cancer cell migration and invasion." (PMID 38706915, 2024). "Additionally, GPNMB, known for its role as a negative regulator of T cell activation, exhibits potent immunosuppressive properties in the context of cancer." (PMID 38706915, 2024). "Blocking GPNMB function is a potentially valuable therapy for cancer by eliminating GPNMB+MDSCs." (PMID 38140790, 2023).
cancer (continued). "Furthermore, GPNMB plays an important role in various diseases in addition to cancer by regulating inflammation and immune responses." (PMID 36263422, 2022). "Thus, although GPNMB is known to play various roles in normal tissues, it has also been reported to be overexpressed in malignant tumors including glioma, hepatocellular carcinoma, and rectal cancer." (PMID 36061142, 2022). "Macrophages-secreted GPNMB induces cancer stemness via CD44 on cancer cells, suggesting that enhanced cancer cell stemness may explain the shorter PFS of this patient, despite high expression of IFN and antigen presentation-related genes." (PMID 36248860, 2022). "Some of the significant cancer hallmark terms are inflammatory response (CD14, CD69, IL10RA), KRAS signaling up (CD37, IL10RA, GPNMB), IL-6/JAK/STAT3 signaling (CD14, CSF2RB), Interferon Gamma Response (CD69, CSF2RB, IL10RA, VCAM1, SLAMF7), TNF-alpha Signaling via NF-kB (CD69)." (PMID 35486660, 2022). "In addition, GPNMB is involved in cancer migration, invasion, progression, and metastasis, as well as poor patient prognosis." (PMID 34440182, 2021). "Although previous work indicated that GPNMB is an anti-metastatic glycoprotein, recent studies question the function of GPNMB in cancer, because GPNMB appears to have a protective role in some types of cancers whereas it may promote metastasis in others." (PMID 34054862, 2021). "The ability to inhibit T cell activation may be an important factor that explains the relationship between GPNMB and cancer." (PMID 34054862, 2021). "Recently, GPNMB has been found to be widely expressed in various types of cells, including melanocytes, macrophages, dendritic cells, and various cancer cells, and is localized in the plasma membrane, melanosomes, and endosomal lysosomal compartment in the cytoplasm." (PMID 34639184, 2021). "Another way that GPNMB might contribute to cancer inflammation is by interacting with molecules involved in tumoral progression." (PMID 34054862, 2021). "Importantly, GPNMB can be targeted therapeutically using antibody-drug conjugates which are in clinical trials for cancer therapy, such as glembatumumab vedotin, providing an entry point for the evaluation of glembatumumab in the treatment of BHD tumors." (PMID 33459596, 2021). "Currently ADCs targeting GPNMB-expressing cancers are under investigation, although Glembatumumab vedotin failed to demonstrated clinical advantages over capecitabine on progression-free survival in the phase IIb METRIC study (NCT1997333), several interesting points remained to be discussed." (PMID 34108545, 2021). "Moreover, higher GPNMB level has been demonstrated to promote angiogenesis, migration, invasion and metastasis of cancer cells." (PMID 34108545, 2021). "Additionally, GPNMB was recently identified as the specific marker and potential molecular therapeutic target in some cancers." (PMID 30484490, 2018). "Previous studies have showed the GPNMB is involved in various physiological and pathological processes, including immune system activation, cell proliferation, angiogenesis, tissue-repair, especially the invasion and metastasis of malignant tumors." (PMID 30671053, 2018). "Because of this link between GPNMB and cancer, we hypothesized that GPNMB could be involved in maintaining a tolerant environment, which promotes a successful normal term pregnancy." (PMID 29123519, 2017). "Anti-GPNMB antibodies are currently in clinical trials for cancer." (PMID 29123519, 2017). "Also, exogenous treatment of cancer cells (expressing low GPNMB/OA) with recombinant GPNMB/OA protein (rOA) significantly facilitated cell invasion and migration, but the effects of rOA was negated by inclusion of a selective RGD peptide." (PMID 26883195, 2016).
cancer (continued). "In malignancies, therapy‐induced senolytic‐resistant SCs may produce growth factors that promote cancer growth, express immune evasion signals such as GPNMB, and release pro‐fibrotic factors that create a matrix shielding cancers from immune clearance, speculations that also need to be explored." (PMID 41462575, 2026). "Surface GPNMB may be a marker of and therapeutic target for cancer stem cells." (PMID 40625923, 2025). "Moreover, the soluble GPNMB from macrophages can promote cancer cell survival and expansion." (PMID 38906852, 2024). "Whether GPNMB+IBA1− cells are these cancer stem cells remains an open issue." (PMID 38566120, 2024). "Consequently, GPNMB tends to be upregulated in both aging and cancer, which could be a response to the inflammatory microenvironment, the underlying mechanism needs to be further studied." (PMID 39263169, 2024). "Because of the properties of high GPNMB expression at the surface of cancer cells but significant expression intracellularly in normal cells, GPNMB-targeting monoclonal antibodies are promising candidates for the treatment of patients with GPNMB-expressing cancers." (PMID 39263169, 2024). "Glycoprotein nonmetastatic melanoma protein B (GPNMB) is a type-I transmembrane protein, also known as dendritic cell heparan sulfate proteoglycan integrin-dependent ligand, that has been demonstrated to be overexpressed in numerous cancers and is associated with a metastatic phenotype." (PMID 36263422, 2022). "There have been no reports of comparative GPNMB expression between primary and metastatic lymph nodes in other carcinomas, and the cause of this is unknown; however, we believe this is important evidence that GPNMB is related to EMT." (PMID 36061142, 2022). "These previous studies suggested that GPNMB might be a potential biomarker in cancer biology." (PMID 34108545, 2021). "Thus, GPNMB seems to modulate the immune response to cancer through several mechanisms." (PMID 34054862, 2021). "Therefore, miR-30p-3b might be speculated to act as a potential key upstream negative regulator of GPNMB and might be related to cancer treatment." (PMID 32833670, 2020). "Therefore, we speculated that hsa-miR-346 acts as a potential key upstream negative regulator of GPNMB and might assist in treating cancer." (PMID 32833670, 2020). "Therefore, we suggest that the NKA may function as a novel “receptor” of the GPNMB extracellular fragment and as an additional therapeutic target for various cancers and/or ALS." (PMID 26988030, 2016). "Proteins such as GDF15, MERTK, MRP2, SMPD-1, GPNMB, GRN, and FSTL1, while less widely recognized, have emerging roles in cancer progression, immune modulation, and metabolic regulation." (PMID 40805206, 2025). "For example, GPNMB-high macrophage subsets in the GBM TME (termed lipid-laden macrophages, can transfer myelin-derived lipids to GBM cells, fueling cancer cell proliferation and recurrence." (PMID 40626360, 2025). "GPNMB in TME is mainly expressed by TAMs, can be cleaved into a soluble form by ADAM10 which then binds to CD44 receptor in cancer cells to induce release several chemokines (CXCL1, CXCL2, CCL2, CCL5 and CCL7) as well as cytokines (IL-6, IL-11, and IL-33)." (PMID 38935134, 2024). "Soluble GPNMB has critical functions; for example, it interacts with CD44 to promote cancer cell stemness and metastasis." (PMID 38585871, 2024). "As introduced in Results, these findings fit with reports of GPNMB/CD44 signaling in mesenchymal, neural, and cancer cells." (PMID 39052353, 2024). "GPNMB and VCAM-1 are bothpotentially powerful targets in the treatmentof several types of cancer because of their high expression and functionin metastasis." (PMID 37067377, 2023). "Taken together, the specific binding to membrane-bound GPNMB andVCAM-1 by each binder warrants further development as DbTEs for immunotherapyagainst GNNMB and VCAM-1 overexpressing cancers." (PMID 37067377, 2023).
cancer (continued). "Similar lysis was also found in GPNMB positive sk-mel-28cancer cells and VCAM-1 positive HuT-78 cancer cells, respectively." (PMID 37067377, 2023). "Based on online literature search, we found that OLR1, GPNMB, PRRX1 and BCAT1 promote cancer migration and invasion in various types of cancer." (PMID 29851214, 2018). "In vivo investigation by in situ hybridization established that ADAM23, GPNMB and PRSS3 expression is localized on blood vessels of human cancer specimens." (PMID 18447899, 2008). "GPNMB is a type-I transmembrane protein that is expressed not only in cancer cells, but also in many normal cells, including KCs, MCs, macrophages, dendritic cells, osteoblasts, microglia, and neurons." (PMID 39947468, 2025). "Currently, several ADC targets exist (TROP2, mesotheline, CEACAM5, DLL3, folate receptor alpha, guanylatcyclase, glycoprotein NMB, CD56, CD70 and CD138) with ADC compounds being tested in other cancer entities whose expression level in cervical cancer is of clinical interest." (PMID 38730739, 2024). "In the present experiments, Abs to block GPNMB or CD44 were effective for at least 35 days despite an expected half-life of 6–8 days in mice, reflecting the advantage of targeting a renewable ESC population as done for cancer therapies." (PMID 39052353, 2024). "Despite the different study field and research direction, we substantiated the synergistic effect between GPNMB and EGFR in the non-cancer field and raised that the interaction between the two functioned in the biological processes and cell differentiation in NSCs." (PMID 36820063, 2023). "GPNMB had been identified as an oncogene in TNBC and GPNMB-expressing cancer cells could be killed by a GPNMB-targeting ADC5." (PMID 34108545, 2021). "Glycoprotein non-metastatic melanoma protein B (GPNMB) is a type I transmembrane glycoprotein that plays an important role in cancer metastasis and osteoblast differentiation." (PMID 34639184, 2021). "Elevated GPNMB is not specific to PD: It is elevated in Alzheimer’s, amyotrophic lateral sclerosis, Gaucher’s and Niemann Pick C diseases, as well as in obesity and numerous cancers." (PMID 41406219, 2025). "In addition, GPNMB, a cell surface protein, also serves as a potential therapeutic target, since a fully human antibody-drug conjugate (ADC) has been developed that targets GPNMB and is being evaluated for treatment of several cancers." (PMID 37095531, 2023). "In addition, the predominant co-expression of GPNMB in myeloid cells and CD44 in cancer cells in chemo-resistant samples may provide us with the mechanism underlying chemo-resistance." (PMID 36248860, 2022). "No reports have examined the positivity of GPNMB in HNSCC by flow cytometry or in other carcinomas." (PMID 36061142, 2022).